APC (APC regulator of Wnt signaling pathway)
Diseases named in the same sentence as APC in open-access papers (continued):
Sharing a sentence is not in itself a finding about the gene and the disease.
tumor (continued). "We also found components of the β-catenin destruction complex, namely Axin1 itself and its key binding partner, the APC tumour suppressor, as well as AMER1 and β-catenin, suggesting that the entire complex is associated with Nkd1 HisC aggregates in Wnt-stimulated cells." (PMID 33025907, 2020). "Loss of APC is the main driver of Wnt-signaling in CRC and its pivotal role has been highlighted by recent studies underlining the importance of continuous Wnt-signaling for tumor maintenance." (PMID 33361772, 2020). "Inactivation of the adenomatous polyposis coli (APC) gene—a tumor suppressor—is a major initiating event in CRC tumorigenesis and leads to overactivation of the Wnt pathway due to β-catenin release from the APC, glycogen synthase, and the axin degradation complex." (PMID 32722203, 2020). "This suggests that APC/Asef could be necessary for angiogenesis to supply tumor cells with an adequate blood supply." (PMID 33105836, 2020). "Analyses were adjusted for tumor size, number of lymph nodes, tumor stage, APC reduced-expression and APC methylation status, the findings revealed APC methylation status shown as an independent prognostic factor that affect survival (HR =3.57, 95%CI=1.27-10.01, P=0.016)." (PMID 33369461, 2020). "It was confirmed that APC could inhibit the Wnt signaling pathway, a carcinogenic signaling pathway in several cancers, and the low expression of APC promoted tumor progression." (PMID 33363011, 2020). "Furthermore, one of our IPEC-J2 cultures showed an insertion in the protein coding region and a large deletion in the splicing site of the adenomatous polyposis coli (APC) gene, which is a tumor suppressor often inactivated in colon cancer." (PMID 32714922, 2020). "APC mutations in the MCR that result in 2–3 intact 20-amino acid repeats are more likely to be found in proximal tumours, while mutations leaving only 1 or no 20-amino acid repeats tend to be present in distal CRC." (PMID 33352971, 2020). "APC restoration leading to tumor regression has been observed." (PMID 32258104, 2020). "Co-expression analysis revealed that METTL14 and ZC3H13 had a strong positive correlation with APC, an antagonist of the Wnt signaling pathway, indicating they might cooperate in regulating proliferation, invasion, and metastasis of tumor cells." (PMID 33363011, 2020). "The Wnt/β-catenin pathway exhibits alterations, including β-catenin accumulation and loss of APC, in some PanNENs, and these alterations are not correlated with tumor grade, tumor stage, or disease-specific survival." (PMID 33329729, 2020). "For example, initial inactivation of APC could increase autocatalytic polymerization of tumor tissues that induces tumors to grow predominantly as a single expansion." (PMID 32079164, 2020). "In CRC, aberrant activation of the WNT/β-catenin signaling pathway, mostly attributed to adenomatous polyposis coli (APC) mutations that occur in 90% of CRC patients, disrupts the WNT gradient, allows hyperplasia of ISCs along the crypt-villus axis, and drives tumor initiation via CSCs19." (PMID 33087710, 2020).
tumor (continued). "And downregulation of APC contributes to tumor progression and development." (PMID 32714979, 2020). "In YSTs, several tumor-suppressor genes (such as RASSF1 or APC) are hypermethylated." (PMID 32999426, 2020). "In this context, the APC role in apoptosis supports tumor suppressor function." (PMID 32258104, 2020). "In addition, miR-135a/b targets the 3’UTR of APC, suppresses the expression of APC gene, and finally activates the downstream Wnt pathway to promote tumor progression." (PMID 30736475, 2019). "APC and KRAS are the most frequent mutations encountered in CRC and our model can express both the mutation simultaneously along with definitive development of neoplasm." (PMID 31766149, 2019). "It has been hypothesized that in addition to the APC activities in the Wnt signaling cascade, the APC molecule may be crucial for tumor initiation by functions in microtubule binding, mitosis, and regulation of the cytoskeleton." (PMID 31003440, 2019). "Moreover, loss of the adenomatous polyposis coli (APC) tumour suppressor in mice results in GP130 upregulation, inducing SRC/YAP and JAK/STAT3 pathways that are needed for tumour formation." (PMID 31091767, 2019). "It has previously been proposed that human CRC tumours have a ‘just-right’ level of Wnt signalling, which may in fact be sub-maximal due to truncated APC proteins that retain β-catenin binding sites." (PMID 30760720, 2019). "The loss of APC in intestinal tumor cells upregulated the expression of DKK2 through β-catenin pathway, which, together with its receptor LRP5, provided an unconventional mechanism for tumor immune evasion." (PMID 31372243, 2019). "A recently developed genetically engineered Xenopus tropicalis model harboring a mutated APC, may yield another DTF tumor model that can be exploited as a platform to define novel therapeutic targets and preclinical validation studies." (PMID 31165043, 2019). "Additionally, due to the tumor suppressive activity of APC/C-Cdh1, it is desirable to specifically target APC/C-Cdc20 complexes." (PMID 31382469, 2019). "In three of these pairs the tumours shared the same driver mutation either in BRAF, APC, or ACVR2A." (PMID 30894686, 2019). "Hypermethylation in tumor promoter regions was a suppressor of APC and RASSF1A genes." (PMID 31772591, 2019). "APC is a tumor suppressor that blocks transition of cells from G1 to S phase." (PMID 31244652, 2019). "Due to mutation status changes of the WNT genes (APC and CTNNB1), NEFH might lose its tumor suppressor role, leading to apoptosis dysregulation." (PMID 31740709, 2019).
tumor (continued). "The tumor suppressor APC, listed on top, interacts with AXIN1, which, in addition, interacts with other Wnt/ß-catenin signaling pathway components and is essential for degradation of ß-catenin in the Wnt/ß-catenin signaling cascade, an important signal transduction pathway in CRC." (PMID 29505855, 2018). "Significantly lower overall survival rate in patients with tumours harbouring alterations in APC/CTNNB1/ZNRF3 in comparison to those without mutation was observed." (PMID 29872083, 2018). "Owing to APC and CTNNB1 mutations, β-catenin signaling is hyperactivated, and several downstream targets of β-catenin, such as c-myc, cyclin D1, and PPARdelta, have been identified as markers of tumor development." (PMID 30275459, 2018). "The tumor suppressor, APC, down-regulates β-catenin, as do Axins I and II (also tumor suppressors)." (PMID 29464056, 2018). "We excised tumor lesions or corresponding healthy mucosa from APC+/min and WT mice, respectively: mRNA analysis by q-PCR indicated that the levels of both αv and β3 subunits were significantly upregulated in small intestine tumors in comparison to corresponding healthy mucosa." (PMID 30140377, 2018). "Similarly, APC deletion or expression of stabilized β-catenin in CBC cells is sufficient for tumor initiation in mice." (PMID 30171151, 2018). "The tumor suppressor PTEN promotes APC/C-Cdh1 activity and cells from mice that overexpress PTEN show APC/C-Cdh1-mediated degradation of PFKFB3 and glutaminase, resulting in a decrease of glycolysis and proliferation, and an increase in resistance to oncogenic transformation." (PMID 30234009, 2018). "Increased tumor grade (Gleason score ≥ 7) has been associated not only with widespread genome hypomethylation but also with promoter hypermethylation of several individual loci, including ABCB1, APC, GSTP1, PTGS2, PYCARD, RARβ2, and RASSFA1." (PMID 29706891, 2018). "APC is a tumor suppressor, frequently inactivated in colorectal and other epithelial cancers." (PMID 29618636, 2018). "The analysis of various mutant combinations allowed the determination that the initiating APC and KRAS mutations act as the drivers of proliferation and tumor growth, while inactivating mutations in SMAD4 block differentiation during tumor growth and being required for metastatic potential." (PMID 29652830, 2018). "In the absence of Wnt ligand stimulation, cytoplasmic β-catenin is targeted for proteolysis by a “destruction complex”, which includes the two tumor suppressors Axin and Adenomatous polyposis coli (APC), and two kinases, glycogen synthase kinase 3 (GSK3) and casein kinase 1α (CK1α)." (PMID 29615557, 2018). "While APC was down-regulated in tumor tissue, this does not necessarily equate mutation, although roughly 80% of the tumors in this study had an APC mutation." (PMID 29464056, 2018). "Indeed, approximately 400 methylation-silenced genes in a single tumor have been found, such as the Ras association domain family 1A (RASSF1A), CHD13 and the adenomatous polyposis coli (APC)." (PMID 28938637, 2017). "APC is a tumour suppressor gene that plays a central role in the Wnt signalling pathway." (PMID 28331556, 2017). "A previous study demonstrated that UBR5 could serve as a tumor suppressor by increasing the stability of APC." (PMID 29296225, 2017). "The mechanism of tumor progression in colitis-associated colon cancer (CAC) differs, however, from that of hereditary and sporadic colorectal cancer, exemplified by the early loss of APC in sporadic pathogenesis, which occurs later in CAC." (PMID 28410235, 2017). "We did however not observe any apparent effects on tumor formation driven by excessive proliferative signaling downstream from APC-deficiency." (PMID 29312533, 2017).
tumor (continued). "Tumor samples with codon 622,625 and 1307 mutations were strongly associated with the negative expression of the APC protein in cytoplasm as shown in immunohistochemistry analysis." (PMID 28576136, 2017). "One study reported that other tumor suppressors resulting in MSS tumors, such as MutYH, PolD, PolE, and NTHL1, might be associated with the pathogenesis of CRC in addition to APC gene mutations." (PMID 29237421, 2017). "Many studies have indicated that the overexpression of DNMT1 could silence vital tumor suppressor genes such as APC, P16, and RUNX3 through DNA methylation." (PMID 28473984, 2017). "Here, we engineered various endogenous APC truncations in WT isogenic cell lines and intestinal organoids using CRISPR/Cas9 genome editing and revealed the functional significance of the CID domain in APC as the critical threshold for pathological Wnt activation and tumor formation." (PMID 29045831, 2017). "The expression of MPC1 was negatively correlated with the MYC oncogene and positively correlated with the colon tumor suppressor APC also supported this hypothesis." (PMID 27911865, 2017). "We analysed the complete 352 bp coding region of exon 14 in the APC gene and found two novel deleterious sequence variations (g.127576C > A, g.127583C > T) changing the codons 622 and 625 to stop codons (Y622* and Q625*) in 10% of tumor samples." (PMID 28576136, 2017). "Previous evidence suggest that APC methylation is not a “second hit” in two hit model of APC mutation in tumor." (PMID 28515349, 2017). "Finally, in our CRC study we determined that a tumor-forming L1 insertion in APC occurred at the earliest stages of tumorigenesis (most likely in a normal colon cell), providing further evidence that normal colon tissues can support somatic L1 activity." (PMID 28561751, 2017). "Interestingly, a recent study showed that blocking of IL-17A in an adenomatous polyposis coli (APC)-mediated colon carcinogenesis model enhanced tumor sensitivity to the anticancer agent 5-fluorouracil." (PMID 28492497, 2017). "It will be interesting to see whether and how hNit1 expression is correlated with the β-catenin, APC and Ras status of tumours." (PMID 27462437, 2016). "Significantly increased nuclear staining was not demonstrated in tumours with either APC multiple mutations (n=12, Welch t-test P=0.37) or single mutation plus inferred allelic loss (n=9, Welch t-test P=0.17), possibly because of small sample sizes." (PMID 27302369, 2016). "Moreover, Phesse and co-workers have observed that partial suppression of JAK/STAT3 signaling in APC-mutant mice is sufficient to diminish tumor growth by reducing Bmi-1 dependent repression of p21 and p16." (PMID 27489351, 2016). "Notably, Sample ID 1736 gained 4 somatic mutations and Sample ID 1461 gained 9 additional somatic mutations in the tumor samples (except for the inherited NRAS G138R and APC V1125A variant, respectively)." (PMID 27121310, 2016). "A frameshift variant in APC (c.4660_4661insA, p.E1554fs) was identified in both the normal and tumor material and was determined to be a de novo germline mutation after sequencing of both parents." (PMID 27799065, 2016). "Meanwhile, the OR of 8 studies revealed that the association between APC methylation and tumor grade was not statistically significant (OR = 0.78, 95% CI [0.51–1.21], I2 = 0%)." (PMID 27478702, 2016). "During the development of colonic tumorigenesis, APC is a canonical tumor suppressor." (PMID 27507058, 2016). "The APC gene is considered to be a tumor suppressor gene, and the silencing of its expression may result in cell-to-cell adhesion disorders and the disruption of the Wnt signaling pathway." (PMID 27478702, 2016).
tumor (continued). "On the other hand, it was also observed that almost 30% of tumours harboured only one APC mutation without inferred allelic loss, most of which were MSS tumours, with a substantial number also lacking any other WNT pathway mutation from our examined list." (PMID 27302369, 2016). "Several outlier genes whose knockdown confers striking vulnerability are tumor suppressors including APC, PHLPP1 and SPEN, while a number of other candidates have been reported to harbor anti-oncogenic activities such as the pro-apoptotic gene MTCH2 and the anti-metastatic RNA chaperone RBM47." (PMID 27296290, 2016). "Besides, in vivo experiments showed that LPS promoted APC knockdown tumor growth while inhibited proliferation of APC wild type." (PMID 26760960, 2016). "Finally, disulfiram exposure promoted PCa cells apoptosis and cell-cycle arrest, reduced tumor volume in xenograft mice, and restored expression of tumor suppressor genes, APC, RAR-β and ER-β through inhibition of DNMT activity." (PMID 27651838, 2016). "Eguren and colleagues identified topoisomerase IIα (TopIIα) as a protein substrate of Fzr and demonstrated that both knockdown of Fzr and inhibition of the APC/C with the inhibitor proTAME, significantly enhance sensitivity of tumour cells to TopIIα inhibitors." (PMID 27655696, 2016). "Thus, it appears (at least in mice) that induction of the Wnt signalling programme favours benign tumour formation and thus additional mutations are required to drive further progression, which may in part overcome some of the pro‐adhesive consequences of APC loss." (PMID 26414675, 2016). "APC methylation, although tumor-specific, does not show a significant association with tumor subtype, age, gender, or stage, indicating it is a general tumor-specific CRC biomarker." (PMID 26884349, 2016). "The effects that were detected were in an APC/β-catenin wild type tumor." (PMID 27070088, 2016). "Following the identification of TopIIα as a substrate of APC/CFzr, Eguren and colleagues found that the combination of proTAME (to inhibit Fzr) and etoposide (to inhibit TopIIα) displayed a synergistic effect in tumour cells." (PMID 27655696, 2016). "Compared with Class 1 tumours, while APCwt (Class 0) tumours still carried substantially worse survival (hazard ratio (HR)=1.94, χ2P=0.0023), the AKP triply mutated tumours with two APC mutations (Class 4) had the worst survival (HR=2.48, χ2P=0.0011)." (PMID 27302369, 2016). "Indeed, inhibiting cell competition suppresses over-proliferation in APC−/− cells, effectively blocking tumor formation." (PMID 26853366, 2016). "Thus, a possible linkage of Class 4 tumours' worse survival with APC's DNA-repair-inhibitory function needs to be further investigated." (PMID 27302369, 2016). "APC/CFzr has been reported as a tumour suppressor, however, two recent reports propose that altering levels of Fzr substrates through inhibition of the APC/C may also have therapeutic use." (PMID 27655696, 2016). "Newer research suggests that deregulation of the mammalian target of rapamycin (mTOR) cell proliferation/survival pathway may play an important role in desmoid tumor biology especially when the APC/β-catenin pathway is disrupted." (PMID 26516394, 2015). "Given the centrality of the APC tumour suppressor to CRC, we decided to use a genetic approach in vivo and in vitro to address the differences in Wnt activation by either mutation of β-catenin or mutation of the destruction complex (APC or GSK3)." (PMID 26240067, 2015). "As APC is a large protein, it has been hypothesised that functions other than just Wnt deregulation may be crucial for tumour initiation." (PMID 26240067, 2015). "The APC protein is a tumor suppressor and normally inhibits Wnt signaling." (PMID 26393419, 2015).